RNU6-119P (RNA, U6 small nuclear 119, pseudogene)
Gene: Small nuclear RNA gene on chromosome 4 (116,839,279 to 116,839,385, forward strand). Ensembl gene ENSG00000201752.
Homologues: Orthologues: chimpanzee U6 (98% identical), macaque U6 (91% identical). Paralogues in human: RNU6-19P (86% identical), RNU6-905P (86% identical), RNU6-1060P (85% identical), RNU6-12P (85% identical), RNU6-13P (85% identical), RNU6-31P (85% identical), RNU6-32P (85% identical), RNU6-536P (85% identical), RNU6-1 (84% identical), RNU6-1024P (84% identical), RNU6-128P (84% identical), RNU6-1316P (84% identical), and 1287 more.